GPR82 (G protein-coupled receptor 82)
Description:
Orphan receptor.
Tractability: Small molecule: it belongs to a druggable protein family. Antibody: UniProt places it where antibodies can reach, with medium confidence; UniProt predicts a signal peptide or a membrane-spanning region; its Gene Ontology location is reachable by antibodies, with medium confidence.
Target class: Family A G protein-coupled receptor; Membrane receptor
Gene: Protein-coding gene on chromosome X (41,724,181 to 41,730,130, forward strand). Ensembl gene ENSG00000171657.
Subcellular location: Cell membrane
Gene Ontology:
Molecular function: G protein-coupled receptor activity
Biological process: adipose tissue development; energy homeostasis; G protein-coupled receptor signaling pathway
Cellular component: membrane; plasma membrane
Homologues: Orthologues: chimpanzee GPR82 (99% identical), macaque GPR82 (99% identical), rabbit GPR82 (91% identical), dog GPR82 (89% identical), pig GPR82 (89% identical), mouse Gpr82 (80% identical), rat Gpr82 (80% identical), tropical clawed frog gpr82 (40% identical). Paralogues in human: P2RY4 (19% identical), P2RY6 (19% identical), P2RY2 (18% identical), P2RY1 (18% identical), OXER1 (18% identical), OXGR1 (17% identical), SUCNR1 (17% identical), FFAR2 (17% identical), HCAR1 (16% identical), HCAR3 (16% identical), HCAR2 (16% identical), GPR31 (15% identical), and 3 more.
Diseases named in the same sentence as GPR82 in open-access papers:
GPR82 is named in the same sentence as 8 diseases in open-access papers, as found by Europe PMC text mining. Sharing a sentence is not in itself a finding about the gene and the disease. The quoted sentences say what the papers report.
diabetes (2 papers, 2011 to 2022). "Therefore, the impact of GPR82 function on energy homeostasis under specific conditions, e.g. diabetes and atherosclerosis, requires further investigation." (PMID 22216272, 2011).
asthma (1 paper, 2024). "In total, 6 genes were upregulated (e.g. CCL3L1, CCL4L2, GPR82) and 20 were downregulated (e.g. JUN, IFITM3, DUSP1, GNG7) in peripheral eosinophils of COPD patients compared to asthma." (PMID 39422548, 2024).
Insulin resistance (1 paper, 2011). Increased resistance towards insulin, that is, diminished effectiveness of insulin in reducing blood glucose levels. "This indicates that diet-induced insulin resistance is significantly reduced in female GPR82-deficient mice." (PMID 22216272, 2011).
metabolic syndrome (1 paper, 2022). A cluster of metabolic risk factors for CARDIOVASCULAR DISEASES and TYPE 2 DIABETES MELLITUS. "Gene silencing of GPR82 mediated by siRNA in vivo decreased the values of systolic blood pressure and triglycerides, and increased HDL cholesterol, during the development of metabolic syndrome induced by fructose intake." (PMID 36362842, 2022).
GPR82 also shares sentences with these, for which no sentence is quoted: atherosclerosis (1 paper); blood cancers (1); metabolic disease (1); Obesity (1).